SNORD114-10 (small nucleolar RNA, C/D box 114-10)
Synonyms: 14q(II-10)
Gene: Small nucleolar RNA gene on chromosome 14 (100,967,052 to 100,967,123, forward strand). Ensembl gene ENSG00000200279.
Gene Ontology:
Biological process: RNA processing
Cellular component: nucleolus
Homologues: Orthologues: chimpanzee SNORD114-10 (99% identical), macaque SNORD114-10 (86% identical). Paralogues in human: SNORD114-18 (88% identical), SNORD114-9 (83% identical), SNORD114-15 (82% identical), SNORD114-21 (82% identical), SNORD114-23 (82% identical), SNORD114-26 (82% identical), SNORD114-22 (81% identical), SNORD114-28 (79% identical), SNORD114-3 (79% identical), SNORD114-29 (78% identical), SNORD114-25 (76% identical), SNORD114-6 (76% identical), and 26 more.